CD163 (CD163 molecule)
Diseases named in the same sentence as CD163 in open-access papers (continued):
Sharing a sentence is not in itself a finding about the gene and the disease.
tumor (continued). "Quantification analysis was done on ROIs (n = 10/slide) and different cell populations including CD3+, CD8+, CD163+, FoxP3+, PD-L1+, and CK+ were analyzed in stromal (CK-) and tumor (CK+) areas, respectively." (PMID 33596250, 2021). "Tumor sections were then stained for the MΦ marker CD163 and LDHB using the PhenOptics multispectral imaging system." (PMID 34158867, 2021). "After Stupp therapy, while totally resected patients showed CD163/FKBP51s+ monocytes almost disappeared, patients with MRI diagnosis of persistent tumor had sustained levels in such circulating monocytes." (PMID 33917598, 2021). "The best overall response rate and progression-free survival (PFS) were analyzed depending on the expression of CD68, CD163, PD-1, LAG-3, TIM-3, CTLA-4, TIGIT, CD163/c-maf in the tumor microenvironment in primary and sequential biopsies." (PMID 34830831, 2021). "Studies have shown that among these individual components, M2 macrophages play an essential role in promoting tumor growth, angiogenesis, lymphangiogenesis, immune tolerance, and anti-tumor immunity, and CD163 is a specific marker for these cells." (PMID 33781288, 2021). "Of these, CD206+, CD204+ and CD163+ Mφs are suggested to represent immunosuppressive Mφs that promote tumor progression, whereas CD169+ Mφs display antitumor properties in HCC." (PMID 35070979, 2021). "Foxp3+ Tregs in tumor tissues were positively correlated with CD163+ macrophages (p = 0.011) and CD8+ T cells (p = 0.021)." (PMID 34733785, 2021). "Although the biology mechanism behind CD86/CD163 ratio is well known, the use of this ratio hasn’t been assessed for predicting tumor recurrence in CRC." (PMID 34512652, 2021). "Using mIF, we confirmed that IRX-2 is associated with increases in sTILs and PD-L1 upregulation in the tumor microenvironment, as well as a shift in the ratio of cytotoxic T cells to CD163+ macrophages and regulatory T cells." (PMID 33413574, 2021). "DTYMK promoted the expression of CCL5 by affecting NF-κB, which led to increased infiltration of CD163+ M2-type TAMs in the tumor microenvironment." (PMID 34795209, 2021). "Tumor-associated macrophage-specific markers CD68 and CD163 were used as a marker of M1 and M2, respectively in this study." (PMID 33808480, 2021). "On the contrary, high T cells and low CD163 macrophages, which were observed at the direct tumor border <10 μm, also correlated with improved OS." (PMID 33803620, 2021). "Patients with high density of tumor cells expressing PD-L1, also showed high density of TAMs CD163+ with PD-L1 expression." (PMID 34181355, 2021). "In keeping with other tumour types, high CD4 and CD8 infiltration is associated with improved DFS in PDAC and increased expression of CD163 macrophages is adversely prognostic." (PMID 33481339, 2021). "All the tumour tissues in these four groups expressed CD163 in the mesenchyme, whereas tumours in the RKO‐shR groups expressed low levels of RBP‐Jκ and tumours in SW480‐R groups exhibited high levels of RBP‐Jκ." (PMID 34655278, 2021). "Both immunocytochemical data and flow cytometry analysis show that NTX or PRO alone or in combination increased the percentage of CD161+ NK cells while they decreased the percentage of CD163+ macrophages at varying degrees in the tumor tissues." (PMID 34638341, 2021). "They detected increased expression of both tumor-associated truncated O-linked glycans and the receptor, macrophage galactose-type lectin (MGL), on CD163+ GAMs in GBM patient-derived tumor tissues." (PMID 34071306, 2021). "There was a strong positive correlation between the infiltration of CD20+ B cells, cytotoxic CD4+ and CD8+ T cells, regulatory FOXP3+ T cells, and CD68+ and CD163+ macrophages in both stroma and tumor nests." (PMID 33494389, 2021). "Interactions of CD163+ macrophages and T cells were identified at the edge of the tumor and the brain (3/8)." (PMID 34691054, 2021).
tumor (continued). "Regression analysis showed a significant strong positive correlation between the cellular densities of CD3 + T-cells and CD68 + TAMs (r = 0.812) and CD163 + M2-polarised TAMs (r = 0.707) in tumor nests." (PMID 34200100, 2021). "By multiplex immunohistochemistry, applied on additional OS biopsies, an important bipotent macrophage-population (CD168+/CD163+), homogenously distributed throughout OS tumor areas, was identified." (PMID 33498676, 2021). "Further quantification of the tumor-specific density of this subset of cells in Ndst1f/f CD11cCre+ mutant versus Cre- control tumor-bearing mice revealed a significantly lower CD163+ cell density in mutant tumors." (PMID 34715561, 2021). "The AOM/DSS group showed an increase in the population of CD163+ cells in the subserosa layer of non-tumor areas, and this effect was recovered by Probio-M9 administration (arrows)." (PMID 33808480, 2021). "Tregs recruitment occurs through the binding of CCR4 on Tregs surface and CCL22 secreted by GBM tumour cells and CD163+ TAMs, under the induction of tumour-derived CCL20 and osteoprotegerin." (PMID 33804731, 2021). "In univariate analysis, the factors with statistical significance were LVI, tumor stage, PR, CD163+ TAMs count, CD56+ NK cells count, and MACC1 mRNA relative expression." (PMID 34577857, 2021). "The investigators also examined the composition of the tumor microenvironment (TME) and found that the tumors had a high proportion of CD163+ macrophages, associated with M2 phenotype known to play a role in immune suppression." (PMID 33478080, 2021). "hrHPV+ tumors had higher infiltration rates of CD14+, CD68+ and CD163+ myeloid cells in the IT tumor compartment (p < 0.001, for all) compared to hrHPV− tumors." (PMID 34194435, 2021). "We have also demonstrated that macrophages infiltrating PC are mainly of an M2 type (CD163+) and correlates with a more aggressive tumor and poor patient prognosis." (PMID 34067757, 2021). "Overall, NACT was associated with significant increases in anti-tumor CD8+, CD3+ TILs, and CD68+ macrophages and had a more variable impact on suppressive FOXP3+ TILs and CD163+ macrophages." (PMID 32852603, 2021). "SHH MB subgroup has increased expression of inflammation-related genes (CD14, PTX3, CD4, CD163, CSF1R, and TGFB2) and significantly higher infiltration of tumour-associated fibroblasts than Grp3 MB and Grp4 MB." (PMID 34195095, 2021). "The numbers of CD163- and CD204-stained cells were also counted in the same way to determine tumor-associated macrophages (TAMs)." (PMID 34244567, 2021). "In the ignored phenotype, IF showed (albeit only in subset of ignored tumors) that very high S100A7 expression by tumor cells (highest of all spatial phenotypes) was accompanied by high frequencies of CD163+ macrophages." (PMID 34580291, 2021). "The levels ratios (tumor vs. control) of APRIL, BAFF, IL-8 and MMP-2 were patient-wise negatively correlated in log scale with CD163 protein expression ratios (tumor/control)." (PMID 33846436, 2021). "Hypoxic and acidic tumour microenvironments are host to immunosuppressive cells including CD163+ M2 macrophages." (PMID 33804486, 2021). "The FSTL3 overexpression was found to significantly upregulate the surface markers of the M2 tumor-associated macrophages (TAMs) (CD206 and CD163)." (PMID 34901156, 2021). "As an immune semaphorin, SEMA4D is able to regulate tumor microenvironment by differentiating monocytes toward tumor-supportive macrophage phenotype, namely, M2 macrophages with high expression of CD163." (PMID 34337054, 2021). "M2 polarised macrophages, such as those expressing CD163, enable tumour growth and invasion through the promotion of angiogenesis and production of matrix metalloproteinases." (PMID 33481339, 2021). "The prevalence of CD14+, CD68+ and CD163+ cells was higher in grade 3 tumors than in grade 1 tumors, both in PT Tumor and IT Tumor compartments." (PMID 34194435, 2021).
tumor (continued). "Friebel and coworkers identified CD163 as a general marker of tumor-invading monocyte-derived macrophages." (PMID 33917598, 2021). "Tumor nests showed significantly higher scores for CD11c(+) cells than in tumor stroma, while the score for CD163(+) cells was significantly higher in tumor stroma than in tumor nests." (PMID 34407796, 2021). "The CD86/CD163 ratio tends to have better predictive values than tumor stage in the training (AUC: 0.682 vs 0.654, p=0.538) and validation (AUC: 0.697 vs 0.659, p=0.586) cohorts." (PMID 34512652, 2021). "In general, CD64 and CD163 plus an array of other markers are used for defining anti-tumor and pro-tumor MPs, respectively." (PMID 34680397, 2021). "The association between tumor-infiltrating CD8+ CTLs, CD163+ M2 TAMs, Foxp3+ Tregs and clinicopathological features." (PMID 34733785, 2021). "Recently, CD68 and CD163 were evaluated in both tumor nests and tumor stroma in 60 specimens of invasive breast cancer." (PMID 33968034, 2021). "The production of IL-10 by the CD163+ macrophages suggested that ST11 K. pneumoniae promoted the accumulation of M2-like tumor-associated macrophages in the lumens of adenomatous crypts." (PMID 34606408, 2021). "We observed that ILT4 knockdown in tumor cells decreased M2-like markers, including CD163, CD206, IL-10, and Arginase 1 but increased M1-like markers including CD80, CD86, IL-12, and TNFαin TAMs." (PMID 33537094, 2021). "Previous studies have reported that the numbers of CD163+ macrophages were higher in tumor microenvironment of cases with a cytotoxic/Th1 signature." (PMID 34485116, 2021). "We developed a prognostic nomogram based on CD86/CD163 ratio and tumor stage that allows for individualized estimation of the 48-month RFS probabilities among stage II-III CRC." (PMID 34512652, 2021). "For instance, a significant decreased in GZMB CD8+ T cell density at 20–30 μm from the tumor epithelium concomitant with an increase in CD163 macrophages correlated with improved OS." (PMID 33803620, 2021). "To examine the effects of senescent tumor cells on the macrophages, we performed immunohistochemical staining with CD163 and CD206 as markers for M2 macrophages and with HLA‐DR as a marker for M1 macrophages." (PMID 33643790, 2021). "Meanwhile, CM from anti-ILT4- or anti-PD-L1-pretreated tumor cells decreased CD163 and CD206 levels in TAMs, and combined antibody group displayed the lowest CD163 and CD206 expression." (PMID 33537094, 2021). "OLFML2B was highly co-expressed with tumor-associated macrophage markers such as CD14, CD163, CSF1R, ITGAM, and MRC1." (PMID 34868901, 2021). "M01 TAMs also expressed other pro-tumor markers (CD204, CD206, CD163) and the anti-tumor marker CD169." (PMID 33906694, 2021). "Cell densities of PD-1+ helper T cells in tumor cell nests were significantly correlated with those of CD163+ TAM in tumor cell nests (R = 0.6787, p < 0.0001)." (PMID 34777389, 2021). "hrHPV+ tumors had markedly higher numbers of CD14+, CD68+ and CD163+ myeloid cells in the intratumoral tumor (IT Tumor) compartment compared to hrHPV− tumors (p=0.001, p < 0.001, p=0.002, respectively)." (PMID 34194435, 2021). "CD163 was positive in the paracancerous stroma of all the tumor samples, also with obvious heterogeneity." (PMID 35095878, 2021). "CD3+, CD4+, CD8+, CD20+, CD57+, CD68+, and CD163+ cell infiltration was compared in samples from adjacent tissues and the tumor center." (PMID 33995627, 2021). "In the present study, 269 advanced CRC lesions were immunohistochemically evaluated for CD47, SIRPA, CD68, and CD163 expression in tumor cells and TAIs." (PMID 33799989, 2021). "CD163+ macrophages were seen in the stroma of tumor with variable numbers, and a higher CD163+ macrophage count was related to LNM, LVI and PNI." (PMID 33765961, 2021). "In parallel with PDX models, increased expression of CD163 was more frequently detected in CREBBPQ929*/EP300I997V tumor samples of the patients than those of CREBBPwt/EP300wt patients." (PMID 33431788, 2021).
tumor (continued). "Analysis of tumor and tumor adjacent tissue further revealed that CD163+ macrophages and TIGIT+ Tregs were enriched in HCC tissue, while cytotoxic CD8+ T cells and NKT cells were enriched in tumor adjacent tissue independent of HBV status." (PMID 34771611, 2021). "In subtotal resected patients, most of the peripheral CD163 monocytes that were FKBP51s− in the preoperative stage had turned into FKBP51s+, suggesting that the persisting tumor stimulated the development of this monocyte subset." (PMID 33917598, 2021). "qRT-PCR analysis of another TAM marker CD163 strongly supported the initial observation, as both tumor types expressed CD163 message levels way above normal controls." (PMID 35366268, 2021). "Quantitative immunohistology and confocal microscopy demonstrated that increased levels of CD163+ monocytes are recruited in the tumor after NAC." (PMID 35237501, 2021). "The IHC and IF results also revealed that MCT1 was frequently present in the margin between tumor tissues and adipose tissues, accompanied by positive expression of CD163." (PMID 33178603, 2020). "We used the median expression of CD68 and CD163 from the stromal samples to dichotomize the matched tumor samples." (PMID 32809114, 2020). "The mean CD163 expression scores in the tumor nests and the tumor stroma were 31.116 ± 28.91 (range: 0.00 to 187.33) and 168.146 ± 97.591 (range: 14.33 to 476.67) cells per mm2, respectively." (PMID 32630659, 2020). "In the AOM/DSS group, the number of CD163-positive M2 macrophages in the tumoral area was significantly increased (71.7 ± 11.2) in contrast to that of the control group (12.7 ± 2.5; p < 0.001)." (PMID 32485960, 2020). "RNA profiling of microenvironment-related genes revealed increased expression of markers for TAMs and resident microglia (Aif1, Itgam, Cd68 and Cx3cl1), and macrophage M1/M2 polarisation (Cd80 vs. Cd163) in knockdown tumours." (PMID 33339831, 2020). "The flow cytometry results showed that the percentage of M2 macrophages (CD163+/CD68+) was increased when M0 macrophages were co-cultured with FOXO1(+) tumor cells." (PMID 33052231, 2020). "Future studies are needed to confirm the prognostic role of tumor PD-L1, stromal CD163, and tumor CD8 in MBC, and further research is needed to see if these are potential therapeutic targets." (PMID 31937323, 2020). "Regarding to the involvement of tumor-associated macrophage (TAM) in the microenvironment, we monitored the expressions of TAM markers including CD68 and CD163 as well as angiogenesis marker CD31 in xenograft slice." (PMID 32327633, 2020). "TME–tumour comparisons remained similar to the paired data, whereas CD3, CD45RO, VISTA, and CD163 were enriched in the TME relative to the tumour." (PMID 33261133, 2020). "Assessment of patient tissues with CD163-positive tumor cells correlated with higher tumor grade, invasiveness, radioresistance and poor progression free- and overall survival in melanoma, breast, CRC, renal cell, and gastric carcinomas." (PMID 32328462, 2020). "The density of total CD68+ TAMs and the proportion of CD68+/CD163+ TAMs were both statistically significantly lower in parenchymal (ie, epithelial) tumor areas compared with tumor stroma." (PMID 32190817, 2020). "Tumor infiltration by M2-like CD163+ CD33+ PD-L1+ macrophages was found in tumor biopsies from all non small cell lung cancer (NSCLC) patients exhibiting hyperprogression." (PMID 32033028, 2020). "Depletion of CD163+ resident macrophages in tumor-bearing mice with lipid nanoparticles reduced tumor growth and progression." (PMID 33194645, 2020). "In their study dense infiltration of CD163+ macrophages into the tumor stroma correlated with tumor grade, tumor size, subtypes, and receptor status." (PMID 33377644, 2020). "Having shown the effect of CD68+ and CD163+ macrophage infiltration, we next observed if the number of iNOS+ or arginase+ cells independently correlated to pathological features of the tumour." (PMID 32843682, 2020).
tumor (continued). "For metastatic BC patients, the numbers of CD163+ macrophages in tumor nest were an independent prognostic marker of reduced OS and DFS." (PMID 33194645, 2020). "CD68 and CD163 expression in tumor stroma were positively correlated with VEGF-A and VEGF-C in NSCLC patients’ tissues." (PMID 33228719, 2020). "In GBs, parenchymal tumour areas enriched in Iba‐1+/CD163+ cells were also enriched in SEL1L+ cells." (PMID 31111685, 2020). "Individuals also with rs22(GC) and rs22(GG) had tumours that had 2-fold elevated median levels of CD163+ Mɸ counts compared to rs(GC)+rs29(TC), which was also significant." (PMID 32882831, 2020). "For example, the high number of CD68+/COX-2 TAMs in the tumor stroma (TS) and high number of COX-2/CD163 in both tumor nest (TN) and TS were observed in tumors of patients with poor survival that was demonstrated by using multiplex immunofluorescence." (PMID 33194645, 2020). "In contrast, M2-like macrophages, characterized by both CD68 and CD163 expression, are considered to promote tumor growth and metastasis by releasing chemokines, which are inflammatory growth factors." (PMID 32607685, 2020). "CD163+ TAMs contribute to the tumor microenvironment in MCC to promote tumor development by inducing lymphangiogenesis and immunosuppressive cells such as Tregs." (PMID 32707850, 2020). "In four patients with widely discordant adjacent LN, increased PTE was associated with increased infiltration of tumor CD8+ T cells and CD163+ macrophages, whereas stromal regulatory T cells were associated with low nodal PTE." (PMID 33344227, 2020). "IHC and immunofluorescent analysis of tumor samples from 102 OC patients of Chinese cohort showed that reduced ratio of M1(HLA-DR+ or iNOS+)/M2(CD163+ or VEGF+) TAMs and the increased densities of COX-2+ TAMs were the predictors of poor prognosis." (PMID 33194645, 2020). "Next, we examined the association between the total monocyte percentage and monocyte subsets and their level of CD163 expression with tumor characteristics." (PMID 32824692, 2020). "We observed that high intra‐tumor CD163‐expressing TAM density is predictive of reduced survival in BC patients." (PMID 32082570, 2020). "Although CD163 is primarily expressed on monocytes and macrophages it has been detected on tumor cells with high malignant potential." (PMID 32328462, 2020). "A study of 150 patients of Spanish cohort demonstrated that CD163+ macrophages were found in tumor invasive front while CD80+ cells located in adjacent normal mucosa in less invasive T1 colorectal cancer that was detected by immunohistochemistry." (PMID 33194645, 2020). "CD163 is a macrophage- and bone marrow-derived monocyte-specific transmembrane protein whose expression is induced by tumor promoting cytokines, such as IL-6 and IL-10, and reduced by inflammatory stimuli, including TNF-α and IFN-γ." (PMID 33212945, 2020). "A higher ratio of CD163+/CD68+ at the invasive front in comparison with the tumor center was also described elsewhere." (PMID 33371444, 2020). "We studied CD163 in the tumor microenvironment and circulation of patients with CRC in relation to clinicopathological parameters." (PMID 32824692, 2020). "In line with previous studies, CD163 is observed to be expressed by almost 40% of TAMs, in particular those that are located at tumor invasive front." (PMID 32962159, 2020). "In particular, we investigated the CD3 marker, which identifies anti-tumor immune populations, and CD163 and FoxP3, which indicate myeloid and T-cell immunosuppressive cell subsets, respectively." (PMID 32899203, 2020). "To evaluate the association between peripheral NLR and intratumoral inflammatory markers, we analyzed neutrophils and CD8, CD4, and CD163+ cells from paired primary and recurrent tumor specimens." (PMID 33330078, 2020). "Depletion of CD163+ TAMs using anti-CD163 immunoliposomes loaded with doxorubicin limits tumor progression in malignant animal models." (PMID 32752088, 2020).